MYH13 (myosin heavy chain 13)
Description:
Fast twitching myosin mediating the high-velocity and low-tension contractions of specific striated muscles.
Synonyms: MyHC-EO; MyHC-IIL
Tractability: PROTAC: ubiquitination databases record sites on it.
Gene: Protein-coding gene on chromosome 17 (10,300,865 to 10,373,130, reverse strand). Ensembl gene ENSG00000006788.
Subcellular location: Cytoplasm, myofibril
Gene Ontology:
Molecular function: actin filament binding; microfilament motor activity; ATP binding; cytoskeletal motor activity
Biological process: muscle contraction
Cellular component: extracellular exosome; cytoplasm; muscle myosin complex; myosin filament; myosin II complex; myofibril; myosin complex
Genetic constraint (gnomAD): Loss-of-function variants: 173 observed, 228.54 expected, observed/expected ratio (o/e) 0.76, 90% interval 0.67 to 0.86. The upper end of that interval is the gene's LOEUF score, 0.86, which puts it in group 3 of 6, group 1 being the genes least tolerant of losing a copy. Missense variants: 2,210 observed, 2,436.7 expected, observed/expected ratio (o/e) 0.91, 90% interval 0.88 to 0.94. Synonymous variants: 877 observed, 935.84 expected, observed/expected ratio (o/e) 0.94, 90% interval 0.89 to 0.99.
Homologues: Orthologues: mouse Myh13 (96% identical), macaque MYH13 (96% identical), rabbit MYH13 (96% identical), guinea pig MYH13 (95% identical), pig MYH13 (94% identical), chimpanzee MYH13 (94% identical), rat Myh13 (92% identical). Paralogues in human: MYH1 (82% identical), MYH2 (82% identical), MYH8 (82% identical), MYH4 (81% identical), MYH3 (79% identical), MYH6 (77% identical), MYH7 (77% identical), MYH7B (66% identical), MYH15 (60% identical), MYH10 (41% identical), MYH9 (41% identical), MYH11 (40% identical), and 32 more.
Diseases named in the same sentence as MYH13 in open-access papers:
MYH13 is named in the same sentence as 3 diseases in open-access papers, as found by Europe PMC text mining. Sharing a sentence is not in itself a finding about the gene and the disease. The quoted sentences say what the papers report.
breast carcinoma (1 paper, 2022). "The UBASH3A and MYH13 variants were functionally assessed in MDA-MB-231 and MCF-7 breast cancer cell lines." (PMID 35625741, 2022). "Four potential breast-cancer-predisposing genes, i.e., UBASH3A, MYH13, UTP11L, and PAX7, were selected for further validation through transfection and ectopic expression of wild-type and mutated constructs followed by mass spectrometry profiling and/or Western blot analyses." (PMID 35625741, 2022).
Dystonia (1 paper, 2018). An abnormally increased muscular tone that causes fixed abnormal postures. "Another candidate variant in MYH13 (rs7807826) did not completely cosegregate with dystonia in this pedigree." (PMID 29770609, 2018).
cancer (3 papers, 2019 to 2022). A tumor composed of atypical neoplastic, often pleomorphic cells that invade other tissues. "MYH13 also has no known role in cancer, but somatic mutations in CRC are found in 2.3% (cBioportal)." (PMID 30809968, 2019). "The study reported that the potential muscle-specific genes expressed in cancer cells were TNNI1, TNNT1, DES, TRDN, MYH6, MYH11, and MYH13." (PMID 36378654, 2022). "Selected candidate genes, i.e., UBASH3A, MYH13, UTP11L, and PAX7, were further evaluated using protein expression analysis but no alterations of cancer-related pathways were observed." (PMID 35625741, 2022).